SMAD4 (SMAD family member 4)
Description:
In muscle physiology, plays a central role in the balance between atrophy and hypertrophy. When recruited by MSTN, promotes atrophy response via phosphorylated SMAD2/4. MSTN decrease causes SMAD4 release and subsequent recruitment by the BMP pathway to promote hypertrophy via phosphorylated SMAD1/5/8. Acts synergistically with SMAD1 and YY1 in bone morphogenetic protein (BMP)-mediated cardiac-specific gene expression. Binds to SMAD binding elements (SBEs) (5'-GTCT/AGAC-3') within BMP response element (BMPRE) of cardiac activating regions (By similarity). Common SMAD (co-SMAD) is the coactivator and mediator of signal transduction by TGF-beta (transforming growth factor). Component of the heterotrimeric SMAD2/SMAD3-SMAD4 complex that forms in the nucleus and is required for the TGF-mediated signaling. Promotes binding of the SMAD2/SMAD4/FAST-1 complex to DNA and provides an activation function required for SMAD1 or SMAD2 to stimulate transcription. Component of the multimeric SMAD3/SMAD4/JUN/FOS complex which forms at the AP1 promoter site; required for synergistic transcriptional activity in response to TGF-beta. May act as a tumor suppressor. Positively regulates PDPK1 kinase activity by stimulating its dissociation from the 14-3-3 protein YWHAQ which acts as a negative regulator.
Synonyms: DPC4; MADH4; JIP; MYHRS
Tractability: Small molecule: a structure with a bound ligand is known; it has a high-quality binding pocket. PROTAC: UniProt records ubiquitination sites on it; ubiquitination databases record sites on it; its protein half-life has been measured.
Gene: Protein-coding gene on chromosome 18 (51,028,528 to 51,085,045, forward strand). Ensembl gene ENSG00000141646.
Subcellular location: Cytoplasm; Nucleus
Subcellular location (Human Protein Atlas): Basal body; Centrosome; Nucleoplasm; Cytosol; Primary cilium tip; Vesicles
Pathways (Reactome):
Developmental Biology: Cardiogenesis; Formation of definitive endoderm; Germ layer formation at gastrulation; Signaling by NODAL; Transcriptional regulation of brown and beige adipocyte differentiation by EBF2; Transcriptional regulation of pluripotent stem cells
Signal Transduction: Downregulation of SMAD2/3:SMAD4 transcriptional activity; SMAD2/SMAD3:SMAD4 heterotrimer regulates transcription; Signaling by Activin; Signaling by BMP; TGF-beta receptor signaling activates SMADs; TGFBR3 expression
Gene expression (Transcription): FOXO-mediated transcription of cell cycle genes; FOXO-mediated transcription of oxidative stress, metabolic and neuronal genes; RUNX2 regulates bone development; RUNX3 regulates BCL2L11 (BIM) transcription; RUNX3 regulates CDKN1A transcription
Disease: SARS-CoV-1 targets host intracellular signalling and regulatory pathways; SMAD2/3 MH2 Domain Mutants in Cancer; SMAD4 MH2 Domain Mutants in Cancer
Metabolism of proteins: Ub-specific processing proteases
Gene Ontology:
Molecular function: DNA binding; DNA-binding transcription activator activity, RNA polymerase II-specific; DNA-binding transcription factor activity; I-SMAD binding; identical protein binding; protein binding; protein homodimerization activity; R-SMAD binding; RNA polymerase II cis-regulatory region sequence-specific DNA binding; sequence-specific DNA binding; sulfate binding; transcription cis-regulatory region binding; transcription coactivator binding; transcription corepressor binding; DNA-binding transcription factor activity, RNA polymerase II-specific; chromatin binding; collagen binding; filamin binding; protein-containing complex binding; RNA polymerase II transcription regulatory region sequence-specific DNA binding; RNA polymerase II-specific DNA-binding transcription factor binding; SMAD binding
Biological process: BMP signaling pathway; cellular response to transforming growth factor beta stimulus; DNA-templated transcription; epithelial cell migration; epithelial to mesenchymal transition; extrinsic apoptotic signaling pathway; intracellular signal transduction; negative regulation of canonical Wnt signaling pathway; negative regulation of cell growth; negative regulation of DNA-templated transcription; neuron fate specification; positive regulation of DNA-templated transcription; positive regulation of extracellular matrix assembly; positive regulation of gene expression; positive regulation of transcription by RNA polymerase II; positive regulation of transforming growth factor beta receptor signaling pathway; regulation of transforming growth factor beta2 production; response to hypoxia; response to transforming growth factor beta; SMAD protein signal transduction; transforming growth factor beta receptor signaling pathway; activin receptor signaling pathway; anatomical structure morphogenesis; atrioventricular canal development; atrioventricular valve formation; and 38 more
Cellular component: activin responsive factor complex; chromatin; cytoplasm; cytosol; heteromeric SMAD protein complex; nucleoplasm; nucleus; SMAD protein complex; transcription regulator complex; protein-containing complex; RNA polymerase II transcription regulator complex
Genetic constraint (gnomAD): Loss-of-function variants: 5 observed, 46.35 expected, observed/expected ratio (o/e) 0.11, 90% interval 0.055 to 0.23. The upper end of that interval is the gene's LOEUF score, 0.23, which puts it in group 1 of 6, group 1 being the genes least tolerant of losing a copy. Missense variants: 253 observed, 578.49 expected, observed/expected ratio (o/e) 0.44, 90% interval 0.39 to 0.49. Synonymous variants: 177 observed, 197.54 expected, observed/expected ratio (o/e) 0.9, 90% interval 0.79 to 1.01.
Gene-disease validity (ClinGen):
ClinGen rates the evidence that SMAD4 causes each of these diseases.
juvenile polyposis/hereditary hemorrhagic telangiectasia syndrome (autosomal dominant): Definitive. An autosomal dominant syndrome caused by pathogenic variants in the SMAD4 gene, characterized by the combined features of juvenile polyposis syndrome (JPS) and hereditary hemorrhagic telangiectasia (HHT).
Myhre syndrome (autosomal dominant): Definitive. Myhre syndrome is characterized by striking muscular build, short stature, reduced joint mobility, brachydactyly, mixed hearing loss and mental retardation of variable severity.
pulmonary arterial hypertension (autosomal dominant): Disputed. Pulmonary arterial hypertension (PAH) is a group of diseases characterized by mean pulmonary artery pressure >20 mmHg and elevated pulmonary arterial resistance leading to right heart failure.
Cancer hallmarks: angiogenesis (promotes); suppression of growth (promotes); invasion and metastasis (suppresses); genome instability and mutations (suppresses); angiogenesis (suppresses); invasion and metastasis (promotes); tumour promoting inflammation (promotes)
Homologues: Orthologues: chimpanzee SMAD4 (100% identical), macaque SMAD4 (100% identical), guinea pig SMAD4 (99% identical), pig SMAD4 (99% identical), rabbit SMAD4 (99% identical), rat Smad4 (99% identical), mouse Smad4 (98% identical), dog SMAD4 (98% identical), tropical clawed frog smad4 (92% identical), zebrafish smad4a (88% identical), zebrafish smad4b (46% identical), Drosophila melanogaster Dad (18% identical), and 2 more. Paralogues in human: SMAD2 (35% identical), SMAD5 (35% identical), SMAD9 (35% identical), SMAD1 (34% identical), SMAD3 (34% identical), SMAD6 (23% identical), SMAD7 (19% identical).
Diseases named in the same sentence as SMAD4 in open-access papers:
SMAD4 is named in the same sentence as 450 diseases in open-access papers, as found by Europe PMC text mining. Sharing a sentence is not in itself a finding about the gene and the disease. The quoted sentences say what the papers report.
pancreatic cancer (512 papers, 2000 to 2026). "Approximately 31%–38% of individuals with pancreatic cancer harbor SMAD4 mutations, which are frequently lost through homozygous deletions or mutations." (PMID 40264765, 2025). "In turn, the gene encoding the tumor suppressor protein SMAD4 is inactivated in 50–55% of pancreatic cancers, and the role of its loss in PC remains controversial but appears to be associated with poorer overall survival and metastasis." (PMID 39361216, 2025). "In pancreatic cancer for example, loss of SMAD4 impairs T-cell infiltration and chemokine production, leading to a poorly immunogenic tumor microenvironment with reduced IFNγ-driven PD-L1 expression." (PMID 41155227, 2025). "Loss of nuclear SMAD4 staining and loss of p16 nuclear staining are present in approximately 55% and 75% of pancreatic cancers, respectively." (PMID 40831554, 2025). "Focusing on critical regulators, such as FSP1, MCU, and SMAD4, along with leveraging the vulnerabilities linked to ferroptosis, presents a promising avenue for enhancing treatment outcomes in patients with pancreatic cancer." (PMID 40427552, 2025). "Contrastingly, treating SMAD4-deficient pancreatic cancer cells with ROS or autophagy inhibitors reversed them to a radiosensitive state and markedly amplified the RT-induced tumor cell apoptosis." (PMID 41041050, 2025). "Previously, we discovered that SMAD4 mutation renders pancreatic cancer resistant to radiotherapy via promotion of autophagy." (PMID 39528473, 2024). "Mutations in the SMAD4 gene have been associated with various diseases, including pancreatic cancer, juvenile polyposis syndrome, and hereditary hemorrhagic telangiectasia." (PMID 38461536, 2024). "Based on our set of findings, our findings offer a new combined therapeutic strategy for SMAD4 deficient PDAC that can significantly reduce pancreatic cancer radiotherapy resistance." (PMID 39528473, 2024). "The incidence of deletion and mutation of tumor suppressor gene SMAD4/DPC4 was 55% in pancreatic cancer." (PMID 38514720, 2024). "The mutations of KRAS and SMAD4, which are key genes identified in human pancreatic cancer, have also been detected on Pan02 cells." (PMID 38547077, 2024). "Together, these data suggest that KDM5B is overexpressed in GEM-treated PDX pancreatic cancer with SMAD4 loss." (PMID 38789418, 2024). "SMAD4 is a specific tumor suppressor gene in pancreatic cancer, and the loss of SMAD4 function is significantly correlated with tumor invasion, poor progression, and poor prognosis." (PMID 38686046, 2024). "To figure out the underling mechanism, we established a gemcitabine (GEM)-treated PDX SMAD4 mutations pancreatic cancer mouse model." (PMID 38789418, 2024). "For instance, TRIM47 has been implicated in promoting tumor progression in colon and pancreatic cancer by degrading SMAD4 and FBP1." (PMID 38199981, 2024). "For example, in pancreatic cancer, the loss of SMAD4 is a common event, and its absence is associated with increased aggressiveness and poor prognosis of the disease." (PMID 39164192, 2024). "We first surgically resected primary pancreatic cancer tissue, IHC assay was used to show the SMAD4 mutations in tumor tissues." (PMID 38789418, 2024).
pancreatic cancer (continued). "In the context of pancreatic cancer, approximately 60% of SMAD4 mutations exhibit loss of heterozygosity, and about 50% involve homozygous deletions or intragenic inactivating mutations." (PMID 39528473, 2024). "Smad4, also known as DPC4, is a critical tumor suppressor gene implicated in various cancers, including hepatocellular carcinoma, breast invasive ductal carcinoma, pancreatic cancer, colorectal cancer, and prostate cancer." (PMID 39596873, 2024). "Therapeutic approaches targeting SMAD4 mutations in pancreatic cancer seem promising, particularly in the realm of T cell-related therapy, indicating potential avenues for immunotherapy." (PMID 38666907, 2024). "In our current study, we further demonstrated that SMAD4 deficiency promotes DSB repair in pancreatic cancer caused by ionizing radiation, as evidenced by more quickly decreased expression of γ-H2AX levels." (PMID 39528473, 2024). "Resistance to PDAC treatment has been associated with SMAD4 loss limiting the vulnerability of pancreatic cancer cells to complex I inhibition via the promotion of mitophagy." (PMID 37790705, 2023). "The purpose of this study was to find synthetic lethal interactions with SMAD4 deficiency to find novel therapeutic strategies for the treatment of patients with SMAD4-deficient colorectal or pancreatic cancers." (PMID 37377893, 2023). "Previous studies have shown that SMAD4 gene mutation can increase the immunogenicity of pancreatic cancer through the tumour's endogenous DNA sensing system." (PMID 37488750, 2023). "Using pooled lentiviral single-guide RNA libraries, we conducted genome-wide loss-of-function screens in Cas9-expressing colorectal and pancreatic cancer cells harboring altered or wild-type SMAD4." (PMID 37377893, 2023). "Since the discovery of SMAD4/DPC4 in 1996, many studies have shown that alterations in SMAD4/DPC4 are closely associated with pancreatic cancer." (PMID 37685308, 2023). "Our data show that RAB10 KO decreases proliferation preferentially of SMAD4-deficient colorectal and pancreatic cancer cell lines." (PMID 37377893, 2023). "The small GTPase protein RAB10 was identified and validated as a susceptibility gene in SMAD4-altered colorectal and pancreatic cancer cells." (PMID 37377893, 2023). "SMAD4 is also mutated or deleted in 10%–15% and 20%–50% of colorectal and pancreatic cancers, respectively, in which its loss of expression is associated with inferior outcomes in patients with colorectal cancer and pancreatic cancer." (PMID 37377893, 2023). "The TGFβ signaling mediator SMAD4 is frequently mutated or deleted in colorectal and pancreatic cancers." (PMID 37377893, 2023). "Pancreatic cancer patients with SMAD4 mutations showed better therapeutic results when a combination strategy was used, consisting of chemotherapy (S-1) and cintilizumab." (PMID 36672865, 2023). "One study at MSK reported that EOPC (n = 95; ≤55 years) patients had higher frequency of SMAD4 mutations than patients with average‐onset pancreatic cancer (AOPC; n = 203, ≥70 years)." (PMID 36999792, 2023). "SMAD4 is one of the major driver genes for pancreatic cancer, its mutation makes pancreatic cancer resistant to radiotherapy." (PMID 36653904, 2023). "Mutations in SMAD4 are related to advanced disease, poor OS and recurrence in resectable pancreatic cancer." (PMID 36081557, 2022). "Deleterious mutations in SMAD4 have been shown to result in pancreatic cancer, juvenile polyposis syndrome, hereditary hemorrhagic telangiectasia syndrome and Myhre syndrome." (PMID 35114952, 2022). "Loss of SMAD4 is observed frequently in pancreatic cancer patients and has been considered as a tumor suppressor gene." (PMID 35159011, 2022).
pancreatic cancer (continued). "The tumor-suppressor genes represented by the missense mutations in SMAD4, which encodes the transforming growth factor beta (TGFβ) signaling, are found in about 55% of pancreatic cancer patients, and are associated with a poor prognosis." (PMID 36556296, 2022). "It has been shown that the depletion of SMAD family member 4 (SMAD4), which is a frequently mutated gene, can also induce high levels of autophagy in pancreatic cancer cells." (PMID 36139006, 2022). "Other studies have shown that loss of SMAD4 expression is associated with metastasis in pancreatic cancer." (PMID 35664782, 2022). "Reduced SMAD4 immunostaining has been associated with reduced survival in lung and pancreatic cancer." (PMID 35144669, 2022). "SMAD4 expression causes radioresistance in pancreatic cancer through the induction of reactive oxygen species and autophagy." (PMID 36142267, 2022). "SMAD4 is an important tumor suppressor gene that is found to be inactivated in approximately 50% of pancreatic cancers and has been associated with a more aggressive clinical course." (PMID 35720978, 2022). "For example, a meta-analysis demonstrated that loss of SMAD4 (SMAD Family Member 4) expression was associated with worse prognosis of patients with pancreatic cancer." (PMID 35769782, 2022). "Having established the biological function of Smad4‐loss in mouse pancreatic cancer cells, we next explored TCGA database cohort of pancreatic cancer patients for immune‐related gene expression." (PMID 35064757, 2022). "Overall, these data suggest that pancreatic cancers with loss of SMAD4 represent a poorly immunogenic molecular subtype, with a relative lack of T-cell infiltration and limited expression of PD-L1." (PMID 35155243, 2022). "This outcome reveals that this combination can be effective in treating metastatic pancreatic cancer, especially in pancreatic cancer patients with SMAD4 and TSC2 mutations." (PMID 34880877, 2021). "have found that defective SMAD4 lead to the radioresistance by increasing persistently higher levels of ROS and promoting the autophagy caused by radiation in pancreatic cancer." (PMID 34434896, 2021). "SMAD4 deletions or mutations have been widely observed in different cancer types, such as colorectal and pancreatic cancers." (PMID 34012911, 2021). "Prospective studies on the role of autophagy inhibition and SMAD4 loss in pancreatic cancer are warranted." (PMID 34002944, 2021). "SMAD4 deficiency induced by genomic deletions or truncated mutations are associated with an inferior prognosis in pancreatic cancer." (PMID 34055620, 2021). "Mutations or deletions in the SMAD4 gene have been shown to result in pancreatic cancer, juvenile polyposis syndrome, and hereditary hemorrhagic telangiectasia." (PMID 34301194, 2021). "Increased levels of autophagy have been observed in pancreatic cancer cells with loss of SMAD4 and SMAD4‐mediated autophagy has been implicated in treatment resistance in pancreatic cancer." (PMID 34002944, 2021).